SIRT3 (sirtuin 3)
Diseases named in the same sentence as SIRT3 in open-access papers (continued):
Sharing a sentence is not in itself a finding about the gene and the disease.
ovarian carcinoma (35 papers, 2012 to 2026). A malignant neoplasm originating from the surface ovarian epithelium. "SIRT3 overexpression has been shown to reduce proliferation and decrease the Warburg-like phenotype of SIRT3-deficient B-cell lymphocytes, whereas knockdown of sirtuin can enhance the migration and invasion of ovarian cancer cells." (PMID 37175631, 2023). "Other studies conducted on ovarian cancer have underlined SIRT3 downregulation in the metastatic tissues and highly metastatic cell lines of ovarian cancer." (PMID 35745656, 2022). "have found that overexpression of SIRT3/5/6/7 is associated with good prognosis in ovarian cancer patients, while elevated levels of SIRT1/4 are associated with poorer patient survival." (PMID 36505774, 2022). "In ovarian cancer, SIRT3 enhances the ability of protein kinase membrane associated tyrosine/threonine 1 (PKMYT1) to promote cell migration and invasion, thus accelerating cancer metastasis." (PMID 35832551, 2022). "It was reported that the induction of apoptosis in the SKOV3 ovarian cancer cell line is associated with the activation of SIRT3; moreover, a decreased level of SIRT3 promotes the metastasis of OC." (PMID 31547300, 2019). "SIRT3, the principal mitochondrial deacetylase, protects against oxidative stress and supports mitochondrial function; its decline with age promotes fibrosis and is associated with poor ovarian cancer prognosis." (PMID 40664665, 2025). "In addition to increasing NAD + level, we supposed that IDO1high ovarian cancer cell-derived EVs might drive abnormal Sirt3 expression linked to mitophagy in endothelial cells." (PMID 38468343, 2024). "Despite the controversial role of SIRT3 in ovarian epithelial cancer, its function in polycystic ovary syndrome (PCOS)—an ovarian granulosa cell-associated disease—is well-defined." (PMID 40777993, 2025). "In epithelial ovarian cancer, SIRT3 prevents mitochondrial superoxide surges to promote cell survival by increasing the activity of the manganese superoxide dismutase (SOD2) in detached cancer cells during the metastatic process." (PMID 40777993, 2025). "A prior investigation revealed that the expression of the SIRT3 protein was markedly reduced in ovarian cancer tissues and in the highly metastatic HO-8910PM cell line." (PMID 40777993, 2025). "IDO1high ovarian cancer cell-derived extracellular vesicles upregulated SIRT3 expression in endothelial cells by increasing acetylation modification." (PMID 40777993, 2025). "Activation of SIRT3 in ovarian epithelial cancer induced apoptosis, decreased mitochondrial membrane potential, and promoted the fission process of mitochondria." (PMID 40777993, 2025). "In another part, SIRT6 and SIRT3 are tumor suppressor gene and considered cancer-associated genes and downregulation of SIRT6 has been found to increase ovarian cancer cell growth." (PMID 39349928, 2024). "It has been reported that decreased levels of SIRT3 promote metastasis of OC, while the induction of apoptosis in SKOV3 ovarian cancer cells is related to the activation of SIRT3." (PMID 36674740, 2023). "Overexpression of SIRT3 has been reported in many cancers like in ovarian cancer, colon cancer and colorectal cancer." (PMID 36809279, 2023). "It has been demonstrated that CT inhibited glycolysis via the STAT3/SIRT3 signaling pathway in ovarian cancer cells." (PMID 37375808, 2023). "In these studies, SIRT3 inhibits ovarian cancer metastasis by repressing Twist expression, thereby impairing EMT progression." (PMID 35745656, 2022). "It was reported that SIRT3 is critical for the inhibition of ovarian cancer invasion and metastasis." (PMID 35571098, 2022). "SIRT3 can regulate ovarian cancer cell autophagy through multiple distinct molecular signaling pathways, including p62, 5’AMP-activated protein kinase, and mitochondrial ROS superoxide dismutase pathways." (PMID 36505774, 2022).
ovarian carcinoma (continued). "The knockdown of SIRT3 in ovarian cancer enhances the migration and invasion towards liver metastasis, while the overexpression of SIRT3 suppresses metastasis dramatically." (PMID 36010594, 2022). "Sirtuin 3 (Sirt3), a member of the sirtuin protein family, performs an essential function in maintaining ovarian cancer intracellular homeostasis in a close mutual monitoring relationship, as well as autophagy." (PMID 35203301, 2022). "Mechanistically, SIRT3 suppresses Twist to inhibit epithelial-mesenchymal transition in ovarian cancer." (PMID 35571098, 2022). "SIRT3 also regulates the sensitivity of ovarian cancer cells to cisplatin by regulating the mitochondrial fission process." (PMID 36505774, 2022). "They indicated that ABT737 enhanced the sensitivity of ovarian cancer cells to cisplatin, which was partially achieved by activating SIRT3 to regulate the mitochondrial fission process." (PMID 33435147, 2021). "It is worth noting that some researchers have also found that, in ovarian cancer cells, activation of SIRT3 can reduce cellular energy stress." (PMID 34675216, 2021). "In ovarian cancer cells, SIRT3 fine-tunes SOD2 activity to adapt to cellular stress and anoikis resistance in order to ensure cell survival." (PMID 32724473, 2020). "In ovarian cancer, SIRT3 expression was significantly downregulated in cancer tissues as demonstrated by both our study and a previous study." (PMID 31113446, 2019). "We also found that SIRT3 knockdown effectively rescued the inhibitory effect of CT on glucose uptake and lactate production in ovarian cancer cells when compared to their controls (P < 0.05)." (PMID 30094960, 2018). "The results of MTT assay showed that CT's inhibitory effect on ovarian cancer cell proliferation was obviously enhanced by the induction of SIRT3 shRNA‐1 when compared to controls (P < 0.05)." (PMID 30094960, 2018). "We found that CT inhibited glucose metabolism in ovarian cancer cells through inducing SIRT3/HIF‐1α signaling pathway." (PMID 30094960, 2018). "In contrast, SIRT3 was reported to suppress tumor growth via induction of growth arrest and apoptosis in colorectal carcinoma, osteosarcoma cells, ovarian cancer, prostate cancer, suggesting that SIRT3 is tumor suppressor in these cancers." (PMID 23230084, 2012). "Furthermore, SIRT3 negatively correlates with STAT3 activity in ovarian cancer, suggesting a suppressive role in inflammation-driven tumorigenesis." (PMID 40664665, 2025). "SIRT3 is downregulated in metastatic ovarian cancer tissues and cells." (PMID 40664665, 2025). "SIRT3 protein level was found to be upregulated in ovarian cancer tissues." (PMID 40777993, 2025). "The endothelial SIRT3-mediated mitophagy, in turn, promoted angiogenesis in ovarian cancer." (PMID 40777993, 2025). "A more recent study used ABT737, a compound that inhibits Bcl-2, to activate SIRT3 expression in ovarian cancer, and the results showed that ABT737 enhanced the sensitivity of ovarian cancer cells to cisplatin due to the overexpression of SIRT3 and the regulation of mitochondrial fission." (PMID 37345199, 2023). "Additionally, SIRT3 regulates mitochondrial ROS levels by activating SOD2, and glycolysis is upregulated by SIRT3 knockdown in anchorage-independent ovarian cancer cells." (PMID 35571098, 2022). "Additionally, SIRT3 mediates the antitumor effects of mitochondrial complex I inhibitors in human ovarian cancer cells by inducing energy stress and apoptosis." (PMID 36505774, 2022). "SIRT3 is highly expressed in anchorage-independent ovarian cancer cells." (PMID 35571098, 2022). "Moreover, SIRT3 enhances the sensitivity of ovarian cancer cells to cisplatin by promoting mitochondrial fission." (PMID 35832551, 2022). "This establishes SIRT3 as a potential therapeutic target for ovarian cancer." (PMID 33435147, 2021). "In addition, SIRT3 activation by ABT737 contributes to ameliorating cisplatin resistance in ovarian cancer." (PMID 32724473, 2020).
ovarian carcinoma (continued). "Moreover, SIRT3 was also downregulated in the metastatic tissues and highly metastatic cell line of ovarian cancer." (PMID 31113446, 2019). "Upregulation of SIRT3 impaired the viability, migration, and invasion of ovarian cancer cells." (PMID 31113446, 2019). "However, SIRT3 has also been shown to be a tumor suppressor in ovarian epithelial cancer." (PMID 40777993, 2025). "In addition, Sirt3 may similarly control autophagy through glutathione S-transferase and JNK-mediated autophagy pathways, and Sirt3 knockdown was shown to relieve S1-induced apoptosis in ovarian cancer cells." (PMID 35203301, 2022). "In this study, we described the inhibitory effects of CT on cell proliferation and glycolysis in ovarian cancer cells through suppressing STAT3/SIRT3 signaling pathway, which indicates that CT may be developed to be a potential drug for the treatment and prevention of ovarian cancer." (PMID 30094960, 2018). "The overexpression of SIRT3 inhibits EMT and cell metastatic capability by down-regulating twist in ovarian cancer cells." (PMID 37894746, 2023). "SIRT3 expression levels were significantly downregulated in the metastatic tissues and highly metastatic cell lines of ovarian cancer, and overexpressed SIRT3 inhibited EMT and ovarian cancer metastasis." (PMID 37894746, 2023). "In ovarian cancer, as a key regulator of EMT, Twist is down-regulated by SIRT3 to suppress the metastasis of the tumor." (PMID 35832551, 2022). "Studies showed that metformin-mediated Sirt3 overexpression encouraged mitochondrial dysfunction and apoptosis via the activation of AMPK in ovarian cancer cells." (PMID 35203301, 2022). "We highlight, in the heterogeneity of ovarian cancer, a characteristic “mitochondrial signature”, characterized by increased mitochondrial biogenesis and altered mitochondrial structure that could result from the cooperation of cAMP pathway and the SIRT3, OPA1, and PHB2 proteins." (PMID 31547300, 2019). "Mechanistically, CT exerted its anti‐tumor effect by targeting STAT3/SIRT3/HIF‐1α signaling pathway in vitro and in vivo, which could be rescued by the introduction of SIRT3 shRNA in ovarian cancer cells." (PMID 30094960, 2018). "However, as a tumor promoter, a recent study showed that SIRT3 could enhance ovarian cancer metastasis by rapidly up-regulating SOD2, which was a new piece of evidence of SIRT3’s role in promoting metastasis in cancer." (PMID 35832551, 2022). "Collectively, these findings demonstrate that FGFR1 functions as a context-dependent tumor suppressor in OC by modulating SIRT3-mediated metabolic reprogramming and histone lactylation, suggesting that targeting the FGFR1-SIRT3 axis may represent a potential therapeutic strategy for ovarian cancer." (PMID 41946672, 2026). "However, the prognostic value of SIRT3 in ovarian cancer has not yet been evaluated." (PMID 31113446, 2019). "In contrast to SIRT3, the roles of the other two mtSIRTs, SIRT4 and SIRT5, are not yet explored in ovarian cancer, though their dual puzzling functions as tumor suppressors and tumor promoters have been reported in other cancers." (PMID 31113446, 2019).
colorectal cancer (34 papers, 2012 to 2026). A primary or metastatic malignant neoplasm that affects the colon or rectum. "The same results have also been observed as a significant association between SIRT3 expression and chemoresistance in colorectal cancer was detected and acute myeloid leukaemia." (PMID 37996927, 2023). "Another study showed that SIRT3 is highly expressed in colorectal cancer cells, and loss of SIRT3 leads to the inactivation of AKT, which in turn affects mitochondrial fission and leads to mitochondrial damage." (PMID 35111368, 2022). "SIRT3 overexpression has been linked to poor survival in many cancer patients, including ER positive breast cancer and colorectal cancer." (PMID 35387119, 2022). "IEC SIRT3 deficiency enhances the production of IL-1β and promotes local TH1 and CTL differentiation in limiting colorectal cancer growth and aggravating colitis." (PMID 41487042, 2026). "In this study, we showed that the nicotinamide adenine dinucleotide (NAD+)-dependent enzyme SIRT3 in IECs is required for local T cell differentiation in colorectal cancer and colitis." (PMID 41487042, 2026). "SIRT3 is highly expressed in colorectal cancer cells with mitochondrial dysfunction, leading to PINK1/parkin-mediated mitophagy." (PMID 40134432, 2025). "Conversely, SIRT3 plays a crucial role in colorectal cancer, acting as the primary mitochondrial deacetylase." (PMID 38213716, 2024). "Studies have exhibited that silencing of SIRT3 is along with decreasing mitochondrial function, and oxygen consumption, which suggests an appealing strategy to render colorectal cancer cells more sensitive to treatment." (PMID 38151790, 2023). "It has been found in recent studies that the SIRT3 deacetylation of SHMT2 can promote the occurrence of colorectal cancer." (PMID 36684675, 2023). "Another study on colorectal cancer cells demonstrated that suppressing SIRT3 re‐sensitized malignant cells to anticancer drugs by inhibiting SOD2, increasing ROS levels, and down‐regulating mitochondria activity." (PMID 38151790, 2023). "We found that GA significantly decreased the invasion and migration of colorectal cancer cells and the overexpression of SIRT3 weakened this effect." (PMID 34747319, 2022). "Compared to the WT group, the GA treatment group presented significant decreases regarding SIRT3 protein levels in colorectal cancer xenograft tissues." (PMID 34747319, 2022). "To study the relationship between GA’s anti-cancer properties and SIRT3, we established SIRT3-overexpressed colorectal cancer cell lines." (PMID 34747319, 2022). "Overall, GA inhibited the proliferation, invasion, and migration of colorectal cancer cells, and induced their apoptosis by inhibiting SIRT3." (PMID 34747319, 2022). "We also found that GA blocks colorectal cancer cells in the G1/G0 phase, inhibiting their proliferation via SIRT3 inhibition." (PMID 34747319, 2022). "Then, we found that GA inhibited the proliferation of colorectal cancer cells in vitro and in vivo, while the overexpression of SIRT3 reversed this effect." (PMID 34747319, 2022). "In the present study, we found that GA significantly decreased SIRT3 protein levels in colorectal cancer cells." (PMID 34747319, 2022). "It has been found that SIRT3 is highly expressed in colorectal cancer tissues and that SIRT3 gene silencing can inhibit the proliferation, invasion, and migration of colorectal cancer cells, besides increasing their apoptosis." (PMID 34747319, 2022). "In colorectal cancer, SIRT3 is an oncogene, highly expressed in colorectal cancer tissues, and related to the sensitivity of colorectal cancer cells to chemotherapy drugs." (PMID 34747319, 2022).
colorectal cancer (continued). "Overall, GA inhibited the proliferation, invasion, and migration of colorectal cancer cells, and induced their apoptosis by SIRT3 inhibition." (PMID 34747319, 2022). "We designed this study to investigate the GA’s effects on the proliferation, invasion, migration, and apoptosis of colorectal cancer cells, and to explore the relationship between GA’s molecular mechanisms and SIRT3." (PMID 34747319, 2022). "Here, we exposed colorectal cancer cells to 0, 5, 10, or 20 μmol/L GA for 24 h and collected them to analyze SIRT3 protein levels by Western blot." (PMID 34747319, 2022). "Sirtuin-3 (SIRT3) has been described as a colorectal cancer oncogene and to be regulated by glycyrrhizic acid (GA)." (PMID 34747319, 2022). "Elucidating the SIRT3/AKT signaling pathway is of great significance for the study of the mechanism of apoptosis in colorectal cancer." (PMID 35111368, 2022). "Then, we exposed WT and SIRT3-overexpressed colorectal cancer cells to 0 or 20 μmol/L GA for 24 h and used a CCK8 assay kit to evaluate the cell viability." (PMID 34747319, 2022). "Loss of SIRT3 triggers activation of mitochondrial fission through the Akt/PTEN pathway and modulates inhibition of colorectal cancer cell survival, growth, and mobility." (PMID 35571098, 2022). "SIRT3 is highly expressed in colorectal cancer, and this high expression is correlated with tumor stage and lymph node metastasis in colon cancer." (PMID 35571098, 2022). "Ac-K88-MTHFD2 is significantly decreased in human colorectal cancer samples and is inversely correlated with the upregulated expression of SIRT3." (PMID 32811824, 2020). "Low glucose increases SHMT2 protein levels by stimulating SIRT3-dependent deacetylation in colorectal cancer cells." (PMID 30367038, 2018). "Here the authors show that acetylation of the lysine-95 (K95) residue negatively regulates SHMT2 expression and activity and is deacetylated by SIRT3 in colorectal cancer." (PMID 30367038, 2018). "Our results, therefore, provide further rationale for the development of SIRT3/SHMT2 antagonists for colorectal cancer therapy." (PMID 30367038, 2018). "In our study, we determined that SIRT3 plays an oncogenic role in colorectal cancer via the deacetylation of SHMT2, which results in increased SHMT2 protein and elevated serine consumption in tumor cells." (PMID 30367038, 2018). "SIRT1 overexpression has been noted in several cancers, including prostate, AML and colorectal cancer, whilst SIRT3 and SIRT7 levels have been demonstrated to be overexpressed in node-positive breast cancer." (PMID 26121130, 2015). "Previous studies have demonstrated the pro-apoptotic effects of Sirt3 in leucocythemia and colorectal cancer cells, whereas the anti-apoptotic activity of Sirt3 and Sirt3-mediated anti-apoptotic mechanism were reported by several other studies." (PMID 25196599, 2014). "Similarly, the deacetylation and activation of serine hydroxymethyltransferase 2 (SHMT2) by SIRT3 enhances the conversion of serine to glycine, promoting colorectal cancer cell proliferation by increasing serine consumption and NADPH levels." (PMID 38773972, 2024). "Moreover, SIRT3 protein levels in specimens of colorectal cancer patients were directly correlated with survival." (PMID 38151790, 2023). "Likewise, by blocking SIRT3, GA prevented colorectal cancer cells from proliferating, migrating, or invading other tissues." (PMID 38322013, 2023). "In the current study, we hypothesized that GA exerted its anti-colorectal cancer activity by SIRT3 inhibition." (PMID 34747319, 2022). "In the present study, we hypothesized that GA exerted its anti-colorectal cancer activity by SIRT3 inhibition." (PMID 34747319, 2022). "In colorectal cancer, SIRT3 is highly expressed in colorectal cancer tissues and the 5-year survival rate of colorectal cancer patients with high SIRT3 expression is lower compared to those with low SIRT3 expression." (PMID 34747319, 2022).